IL6 (interleukin 6)
Diseases named in the same sentence as IL6 in open-access papers (continued):
Sharing a sentence is not in itself a finding about the gene and the disease.
diabetes (continued). "Besides, the Nurses' Health Study and the Health Professional Follow-up Study, including 2691 diabetics and 3237 control subjects, demonstrated that there is no data to support a substantial association between IL-6 polymorphisms and circulating IL-6 levels." (PMID 25815341, 2015). "Finally, studies have demonstrated the existence of a chronic systemic inflammatory state in diabetes, including endothelial dysfunction, platelet hyperactivity, increased inflammatory markers such as C-reactive protein, interleukin-6 (IL-6), and tumor necrosis factor-α (TNF-α)." (PMID 24386004, 2013). "This study describes novel observations regarding the differences in acute inflammatory responses of IL-6, IL-10, and IL-18 for severely obese patients with type 2 diabetes mellitus (DM) from the responses of lean patients." (PMID 24555158, 2013). "Testing the contribution of IL-6 to disease in mice with underlying comorbidities, such as diabetes, may reveal roles for IL-6 in H1N1pdm pathogenesis not seen in our healthy mouse model." (PMID 22679491, 2012). "We selected these markers, including IL-6, because increased levels of these inflammatory cytokines (IL-6 and TNF-α), as well as downstream proteins such as C-RP, ferritin and fibrinogen, have been implicated in the inflammatory response seen in COPD and diabetes." (PMID 20659337, 2010). "TNF-α (B = 1,7, P = 0,01) and IL-6 (B = 1,51; P = 0,04) levels remains significantly elevated after adjustment for sex, age, left ventricular ejection function, body mass index, coronary heart disease, smoking, hypertension and diabetes mellitus with linear regression analysis." (PMID 19909503, 2009). "While established protein markers such as IL-6 and CRP reflect inflammation status, they lack exposure-specificity and are strongly influenced by chronic comorbidities, most notably diabetes mellitus (DM)." (PMID 41596268, 2026). "Prior to diabetes onset, UCD‐T2DM rats had significantly higher circulating levels of IL‐6 and IL‐1β, and these elevations persisted throughout disease progression, with only CRP showing a significant increase at 8 weeks post‐onset." (PMID 42086336, 2026). "It is also involved in the treatment of metabolic diseases, such as diabetes, inflammation, and cancer, by modulating signaling pathways (NF-κB, PI3K/AKT/mTOR, RAS/RAF) and inflammatory markers (IL-6, IL-1β, TNF-α)." (PMID 42282446, 2026). "Our study results indicate that in diabetic rats, LYC reduces the expression of Cas-3, IFN-α, IL-6, and TNF-α, crucial cytokines in the pathogenesis of diabetes." (PMID 39968090, 2025). "In this study, we demonstrated that diabetes, LDL-C, and elevated serum IL-6 levels serve as independent predictors of CMVO, and that thrombus expression of sCD40-L, hs-CRP, and VCAM-1 is closely associated with microvascular obstruction." (PMID 40988197, 2025). "By modulating inflammatory markers such as CRP, IL-6, and TNF-α, exercise can help alleviate both the physical and psychological burdens of diabetes." (PMID 40860530, 2025). "Studies in animal models have shown that BAT transplantation restores euglycemia, lowers levels of pro-inflammatory cytokines such as interleukin-6 (IL-6) and tumor necrosis factor-alpha (TNF-α), and reverses clinical symptoms of diabetes." (PMID 41511338, 2025). "Its lack of association with IL-6 in the present work may therefore reflect the multifaceted nature of its biology, with contributions from microbial translocation, metabolic stress, and immune activation that differ across diabetes phenotypes." (PMID 41010714, 2025). "Considering the cytotoxic impact of alloxan-induced diabetes on various organs, such as the brain, pancreas, liver, and kidneys, we analyzed TNF-α and IL-6 levels in brain and liver tissues at the end of the experiment." (PMID 41020842, 2025).
diabetes (continued). "A logistic regression model including variables with significant between-group differences identified diabetes (OR 2132.35, P = .037), LDL-C (OR 37.54, P = .039), and IL-6 (OR 1.83, P = .020) as independent predictors of CMVO." (PMID 40988197, 2025). "Central cytokine linking CKD, diabetes, and CVD; ↑ IL-6 and CRP correlate with low eGFR; therapeutic target." (PMID 41154568, 2025). "Future research should explore markers of systemic inflammation such as IL-6 or TNF-alpha to complement the analysis of perilesional tissue and evaluate the influence of specific comorbidities such as diabetes or renal failure." (PMID 39859129, 2025). "Clinical studies indicate that dapagliflozin reduces IL-6 levels in patients with CKD and diabetes, highlighting a direct anti-inflammatory effect." (PMID 40141782, 2025). "Similarly, the European Prospective Investigation into Cancer and Nutrition (EPIC)-Potsdam study reported that higher levels of IL-6 and CRP were associated with an increased risk of T2DM in a European cohort, reinforcing the inflammatory hypothesis of diabetes." (PMID 41523554, 2025). "Due to high heterogeneity, we conducted subgroup analyses stratified by patient characteristics, clinical and biochemical parameters, carotid intima-media thickness, IL-6 levels, CTRP9 levels, smoking, hypertension, and diabetes." (PMID 40600192, 2025). "Recent studies also showed that SGLT2i had anti-inflammatory effects in patients with type 2 diabetes mellitus, reducing not only CRP levels but also TNF-α and IL-6." (PMID 40134442, 2025). "The presence of prediabetes, diabetes, hypertension, or atherogenic dyslipidemia in obese individuals was not shown to significantly affect inflammatory parameters (CRP, IL-6)." (PMID 40005412, 2025). "A chronic condition characterized by low-grade inflammation occurs in diabetes, marked by elevated levels of pro-inflammatory cytokines such as TNF-α, IL-1, and IL-6." (PMID 40149566, 2025). "For example, patients suffering from conditions such as high blood pressure, cholesterol, and diabetes (e.g., N4, N5, N9) demonstrated distinct MPO and IL-6 responses." (PMID 39852209, 2025). "Fangchinoline, another major active component of S. tetrandra, effectively downregulates IL-6 and TNF-α levels by inhibiting p38 MAPK pathway activation, while improving the levels of GLU, Cr, ALB in STZ-induced diabetes rats." (PMID 41031161, 2025). "Participants with diabetes had significantly higher hs‐CRP, IL1‐β, TNF, IL‐6 and IFG levels compared to the controls." (PMID 40525652, 2025). "In a randomized controlled trial, daily supplementation with 250 g of frozen red raspberry for 4 weeks was associated with significantly lower levels of inflammation biomarkers, particularly IL-6 and TNF-α, in adults with established type 2 diabetes mellitus." (PMID 41156509, 2025). "Melatonin decreases NF-κB, leading to decreased TNF-α, IL-6, iNOS, and COX-2 in sciatic nerves and improved motor nerve conduction and nerve blood flow in the rat model of diabetes." (PMID 40002826, 2025). "In diabetics, the development of COVID-19 disease is influenced by the upregulation of ACE-2, elevated levels of interleukin-6, and the impaired function of T cells." (PMID 40142738, 2025). "IL6 and TNF-α plays an important role in the development of inflammation-mediated diabetes and neuropathy." (PMID 41264657, 2025). "Compared with the non-CMVO group, the CMVO group differed significantly in 6 baseline variables: prevalent diabetes, door-to-wire (D to W), LDL-C, BMI, serum IL-6 levels, and mean LVEF (all P < .05)." (PMID 40988197, 2025). "In diabetes with MAFLD, TNFRSF1A activation induces NF-kappa B translocation, resulting in the production of pro-inflammatory factors like IL-6 and TNF-α, which exacerbate liver inflammation." (PMID 40918148, 2025). "This study confirms that diabetes, LDL-C, and serum IL-6 levels are influential factors in the occurrence of CMVO." (PMID 40988197, 2025).
diabetes (continued). "Our findings further support this model, demonstrating that HgCl2 exposure, in conjunction with diabetes, significantly enhances TNF-α and IL-6 levels in both the hippocampus and PFC when compared to diabetic rats without HgCl2 treatment." (PMID 40726602, 2025). "Among the circulating cytokines, IL-6 plays a central role as a pleiotropic pro-inflammatory mediator linking CKD, diabetes, and cardiovascular disease." (PMID 41154568, 2025). "The markers of inflammation involved in the bidirectional relationship between OSA and diabetes are tumor necrosis factor-α (TNF-α), interleukin-6 (IL-6), and C-reactive protein (CRP)." (PMID 41155523, 2025). "Older adults also tend to exhibit elevated baseline inflammatorymarkers (e.g., IL-6, CRP) and distinct diabetes pathophysiology—primarilydriven by β-cell dysfunction in older populations versus insulinresistance in younger groups." (PMID 41356294, 2025). "NLRP3/IL-6/IL-1/TNF-α expression was reduced, and diabetes/hyperglycaemia-induced oxidative stress was suppressed, as evidenced by decreased 8-isoprostane and elevated superoxide dismutase-2 levels in vitro and in vivo." (PMID 41214779, 2025). "Diabetes induction in the positive control group by STZ increased FBS, HbA1c, and IL-6, whereas vanillic acid treatment exhibited a protective effect in rats with STZ-induced diabetes as revealed in the reduction of the elevated FBS." (PMID 38577302, 2024). "Age > 70 years, smoking history, diabetes history, prolonged use of perioperative antibiotics, and elevated CRP, IL-6, and IGF-1 levels on the 1st day after surgery have an impact on postoperative lung infection in elderly patients with LC." (PMID 39495987, 2024). "Consistent with previous studies, our findings demonstrate elevated levels of TNF-α, IL-6, and NF-kB in STZ-induced diabetic rats, reinforcing the link between diabetes and cardiac inflammation." (PMID 39496097, 2024). "Diabetes significantly increased serum levels of TNF-α and IL-6 in diabetic control rats and vehicle-treated rats compared to normal controls." (PMID 39144694, 2024). "We selected AKT1, IL-6, and PPARG as the core targets for gut microbiota metabolite regulation of diabetes based on their highest DC values." (PMID 39707185, 2024). "Elevated levels of pro-inflammatory cytokines, including IL-1β, IL-6, and TNF-α, are often observed in diabetic mellitus patients." (PMID 39050988, 2024). "The PPI network indicated AKT1, IL-6 and PPARG as hub genes that are involved in the mechanism of diabetes." (PMID 39707185, 2024). "A decrease in muscle strength is associated with a rise in inflammatory markers such as tumor necrosis factor-alpha (TNF-alpha), interleukin-6 (IL-6), and c-reactive protein (CRP), which can trigger the incidence of diabetes." (PMID 38276133, 2024). "IL6, a versatile cytokine involved in immune and inflammatory responses, plays an important role in the development of DKD in individuals with diabetes." (PMID 38654354, 2024). "Higher expression of proinflammatory factors such as IL-1β, IL-6, and TNF-α and accumulation of AGEs in a diabetes-induced inflammatory environment can all harm the BBB." (PMID 38645427, 2024). "In chronic conditions, gene encoding pro-inflammatory cytokines such as interleukin (IL)-1, IL-2, IL-6, Tumor necrosis factor (TNF)-α, and Monocyte chemoattractant protein (MCP)-1 play crucial roles in diabetes." (PMID 38164478, 2024). "IL6 and its receptor, IL6R, appear to directly connect diabetes to schizophrenia, with multiple connections bridging through the other highlighted processes including GABAergic neurons, oxidative stress, and neuronal plasticity." (PMID 38573526, 2024). "RS treatment significantly decreases the levels of proinflammatory cytokines, HbA1c, IL-6, TNF-α, and IL-1β in diabetes in the elderly." (PMID 38903985, 2024). "For instance, a direct relationship between IL-6 concentrations and CIMT in patients with type 2 diabetes mellitus has been reported." (PMID 37838929, 2024).
diabetes (continued). "Another observational study focused on patients with non-thyroidal illnesses, including a subset of patients with diabetes, and demonstrated that only FT3 and IL-6 had positive relationships." (PMID 39525855, 2024). "We conducted a comparative analysis of baseline marker levels between the study and control groups, including adiponectin, leptin, IL6, TNFα, IGF1, and IGF2, while also adjusting for BMI, parity, and diabetes." (PMID 38339282, 2024). "At first, we explored the expression of IL6 and IL6R in human pancreatic islets and other metabolic tissues, as well as their correlation with diabetes status, using publicly available datasets." (PMID 38667300, 2024). "This meta-analysis aimed to examine the influence of chia consumption on three inflammatory markers: CRP, IL-6, and TNF-α in individuals with type 2 diabetes mellitus or overweight." (PMID 39703891, 2024). "Age > 70 years, smoking history, diabetes history, prolonged use of perioperative antibiotics, and elevated CRP, IL-6, and IGF-1 levels on the 1st day after surgery have an impact on postoperative lung infection in elderly LC patients." (PMID 39495987, 2024). "Here, we specifically detected reduced expressions of IL1β, IL6, IL10 and VEGF-A in M1/proinflammatory macrophages at the inflammatory stage in diabetes." (PMID 38270651, 2024). "The results offer us a comprehensive understanding of the therapeutic effects of previously identified target proteins, including AKT1, IL6, PPARG, JUN, CASP3, EGFR, and PTGS2, in the context of diabetes intervention." (PMID 39707185, 2024). "At the end of treatment, compared with control group, in diabetes, MIRI of diabetes and treatment groups the myocardial TNF-α and IL-6 levels were significantly increased, respectively (P < 0.05)." (PMID 38422326, 2024). "Hypertension, diabetes mellitus, APACHE II score ≥ 15, procalcitonin, CRP, IL-6 and lactate dehydrogenase had significant effects on the development of hypoactive delirium compared with the no delirium group (p < 0.05)." (PMID 38523173, 2024). "Like astaxanthin, it was found that metformin (used as a first-line therapy for type 2 diabetes mellitus) can decrease the cellular level of NF-κB which leads to decreasing the cellular levels of TNF-α, IL-1β, and IL-6." (PMID 39693313, 2024). "In present study, inflammatory cytokines such as IL-6, IL-8 and TNF-α were assayed to assess the impact of diabetes on immunological responses." (PMID 38933114, 2024). "Consequently, the significant reduction in the expression of IGFBP-3 and IL-6, as a result of the inhibitory effects of these metabolites, leads to the emergence of abnormal blood glucose levels and the accompanying vasculopathy during the occurrence of diabetes in this study." (PMID 39206042, 2024). "Among these biomarkers, marked increase in IL-6, IL-8, ICAM and VCAM were significantly higher in diabetics plus PAD as compared to DM and healthy individuals." (PMID 38961103, 2024). "In our study, we found that an APACHE II score ≥ 15; diabetes mellitus; and high procalcitonin, lactic dehydrogenase, BNP, CRP and plasma IL-6 levels were significant variables in the univariate analysis (p < 0.05)." (PMID 38523173, 2024). "In terms of inflammation pathways, chronic inflammation markers such as high-sensitivity CRP, IL-6, and TNF-α have been shown to be elevated prior to the onset of diabetes." (PMID 38188453, 2024). "PHE significantly improved the diabetes state in a dose-dependent way by decreasing leptin and increasing GCK, most likely via reducing ROS generation and inflammatory molecules like IL-6 and TNF-α." (PMID 38234664, 2024). "Inflammatory processes are initiated during diabetes, resulting in the formation of inflammatory molecules such as tumor necrosis factor α (TNF-α), interleukin 1β (IL-1β), interleukin 6 (IL-6), and interleukin 18 (IL-18)." (PMID 39684653, 2024).
diabetes (continued). "Taken together, our data identify IL-6 as a bridge connecting PANDER and GLP-1 in the STC-1 cells, demonstrating potential therapeutic targets for diabetes treatment by targeting the PANDER–IL-6–GLP-1 axis." (PMID 39235859, 2024). "In our study, at the end of treatment, compared with MIRI of diabetes group, the myocardial TNF-α and IL-6 levels in treatment group were significantly decreased." (PMID 38422326, 2024). "A higher proportion of patients in higher IL-6 terciles were current smokers, had a family history of CHD, had diabetes, and had hypertension at baseline (P < 0.001 for all)." (PMID 39077632, 2024). "In terms of SCFAs, for flaxseed oil exerted anti-diabetes action on streptozotocin-nicotinamide-induced rats, the acetic acid was negatively correlated with TNF-α, IL-1β, IL-6, and IL-17A." (PMID 39403395, 2024). "Nine characteristics were determined using Lasso regression: globulin, G/A, diabetes, renal colic, hemoglobin, CRP, IL-6, urine bacterial count and HU value of effusion." (PMID 38896174, 2024). "However, diabetes is also a cardiovascular risk factor, and its impact on the prognosis of MMD has been reported in previous studies, and this might be seen as a way in which IL-6 could influence the functional outcome of MMD." (PMID 36769472, 2023). "The analysis of individual studies on miR-146 in the context of diabetes yielded a heatmap that showcased the prevalence of several genes, namely IRAK1, TRAF6, IL-6, TNF-α, NUMB, EGFR, and TGFβ-1, among others." (PMID 37560309, 2023). "We included in the model (gender, hypertension, AKI, febrile (yes), CKD, age, SAA, IL-6, CRP, diabetes and proteinuria." (PMID 38203482, 2023). "JNK is a subfamily of MAPKs and plays a critical role in the regulation of insulin signaling, inflammation, apoptosis, and caspase-3 activity in diabetes and the upregulation of pro-inflammatory cytokines such as MCP-1, IL-6, IL-8, and TNF-α in AD pathology." (PMID 38006400, 2023). "On the other hand, when adjusting for age, sex, hypertension, diabetes mellitus, ALT, AST, GGT, creatinine, and uric acid (Model 2), only IL-6, IL-10, TNF, and IP-10 levels remained significantly associated with AF." (PMID 36834735, 2023). "The Mitchelstown cohort of the Cork and Kerry Diabetes and Health Diseases Study in Ireland reported that levels of inflammatory biomarkers (i.e., CRP, IL-6 and TNF-α) were lower in individuals with higher HEI-2015 scores." (PMID 37347305, 2023). "Hypervolemic patients were older, more frequently had diabetes and showed increased CRP and IL-6 levels." (PMID 38139378, 2023). "The overexpression of cytokines IL-1β, IL-6, and TNF-α is known to affect systemic acute inflammatory syndrome, chronic immune disease, pain, cardiovascular disease, and diabetes." (PMID 37764215, 2023). "Regarding diabetes, it has been reported that inflammatory factors such as TNF-α, IL-1ß, IL-6, and IL-18 are increased in diabetic patients, contributing to insulin resistance through the JNK and IKKb/ NFkB pathways." (PMID 36832168, 2023). "In the KEGG pathway map, the AGE-RAGE signaling pathway in diabetes complications includes AKT, IL-6, STAT3 and other targets, which all play an important regulatory role in the AGE-RAGE pathway." (PMID 37745719, 2023). "Protein lysates of individual retinas (n = 9/group) were collected for automated Ella quantification of IL-1β, IL-6, and TNF-α; 2 months after diabetes was confirmed." (PMID 36674854, 2023). "The treatment of the STZ-induced diabetes with the bovine extract showed an improvement of 76.77% and 41.82% for TNF-α and IL-6, respectively, while the improvement with the sheep extract reached 73.74 and 95.45%, respectively." (PMID 37764820, 2023).